APOE (apolipoprotein E)
Diseases named in the same sentence as APOE in open-access papers (continued):
Sharing a sentence is not in itself a finding about the gene and the disease.
tauopathy (continued). "In brief, although these effects need further clarification, especially the impact of different APOE genotypes on tau hyperphosphorylation, these findings indicate that APOE dysfunction affects tauopathies in the brain." (PMID 39814004, 2025). "To validate the regulatory role of APOE ε4 on hub genes and its impact on tau pathology, we extracted female P301S tauopathy mice RNA-seq data GSE254103 for further analysis." (PMID 41409615, 2025). "Studies have also demonstrated that mice expressing ApoE4 in tauopathy models exhibit more severe tau-induced neurodegeneration compared to other isoforms, while mice lacking ApoE are protected from this effect." (PMID 39944166, 2025). "A study conducted on a genetically modified mouse model of tauopathy, expressing human ApoE isoforms, revealed a decrease in gliosis, tau pathology, and neurodegeneration." (PMID 39944166, 2025). "The EFAD mouse line combining mutations in APP and PSEN1 with human APOE isoforms provides a platform to study the effects of APOE on Aβ deposition, tauopathy, neuroinflammation, and synaptic function." (PMID 40420360, 2025). "APOE ε4 amplifies tau pathology via hub genes: In P301S tauopathy mice, female APOE ε4 boosted expression of Lrp10, Ltbp2, Lamc1, and Rbms2, revealing a potential link to the acceleration of tau-driven neurodegeneration." (PMID 41409615, 2025). "A recent study demonstrated the impact of the gut microbiota on tauopathy of human APOE isoforms in a tau-transgenic mouse model." (PMID 38472255, 2024). "In order to identify novel treatment targets for AD and other tauopathies, detailed knowledge about the mechanisms by which ApoE influences tau pathology is highly desirable." (PMID 39524360, 2024). "We also postulate that tauopathy can be regulated by metabolic abnormalities such as lipid dysfunction controlled by apolipoprotein E (ApoE), which is an essential ligand for the uptake and clearance of atherogenic lipoproteins." (PMID 39857613, 2024). "Lastly, a recent study identified that microglia-mediated infiltration of T cells is a driver of neurodegeneration in tauopathies, but only in the presence of APOE." (PMID 38658964, 2024). "In bacterial-free tauopathy mice, the level of pTau in the hippocampal area decreased, and microglia and astrocytes remained in a homoeostatic state in a sex- and APOE-dependent manner." (PMID 38472255, 2024). "The impact of ApoE genotypes, particularly ApoE4, on AD-related tauopathy is still debated due to a possible Aβ-ApoE connection and its effect on tauopathy progression." (PMID 39857613, 2024). "Although these studies were conducted on tauopathy mouse models, they suggest the potential role of APOE isoforms in disease pathogenesis." (PMID 39272762, 2024). "To further dissect the relationship between HMGB1, APOE genotype, tauopathy, and aging, we assessed the extent of neuronal HMGB1 translocation in 6-month-old PS19-E4 and PS19-E3 mice." (PMID 37863057, 2023). "The GM of a mouse model of tauopathy (P301S tau transgenic mice) expressing human ApoE isoforms (ApoE3 and ApoE4) was changed by germ-free conditions or short-term antibiotic treatment in early life." (PMID 37065853, 2023). "Previous studies have highlighted how APOE genotype affected tauopathy in tau transgenic animals, in viral-mediated tau overexpression cohorts and in K18-tau seed injected tau transgenic animals." (PMID 37337279, 2023). "This study also provides potential molecular and cellular mechanisms by which the APOE-R136S mutation confers protection as potential targets for therapeutic development against APOE4-related AD and tauopathies." (PMID 37957317, 2023). "The isoform-specific interactions between apoE and tau have become of interest not only in AD research, but also for other tauopathies such as frontotemporal dementia (FTD), chronic traumatic encephalopathy (CTE), and corticobasal degeneration (CBD)." (PMID 36348357, 2022).
tauopathy (continued). "According to some studies, astrocytes modulate the intensity of microglial response in either amyloidogenic and tauopathy models in an APOE-dependent manner." (PMID 35628216, 2022). "At the site of injection, PS/E3H mice accumulated equivalent burden of AT8 tauopathy in both ipsilateral and contralateral hippocampus, while the other APOE genotypes (E2H and E4H) showed lower levels of ptau pathology." (PMID 35440098, 2022). "The APOE ε4 mechanism related to NDDs is yet to be understood; hence, it has been reported that APOE ε4 affects Aβ aggregations, tauopathy, Lewy bodies, inflammations, and so on, and it has been considered as the main genetic risk factor of AD." (PMID 36501161, 2022). "Single nucleotide polymorphism (SNP) of APOE ε4 phosphorylates tau protein and forms NFT and the loss of neuronal function in CNS, as well as causing neurodegeneration due to the tauopathy of AD." (PMID 36501161, 2022). "Given the tight link between AD and tauopathy, the role of ApoE in tauopathies has also been examined." (PMID 34575087, 2021). "More recently, the same group found that astrocyte specific removal of ApoE E4 allele markedly decreased phosphorylated Tau and Tau-associated neurodegeneration, which suggested that astrocyte-derived ApoE4 is a major regulator of tauopathies." (PMID 34575087, 2021). "It is known that APOE ε4 drives the production of Aβ, the accumulation of Aβ fibrils in AD patients, exacerbates tau-mediated neurodegeneration in a mouse model of tauopathy and affects CSF αSyn levels in the prodromal phase of sporadic and familial AD." (PMID 33213513, 2020). "APOE4 significantly aggravated tau-mediated neurodegeneration in a tauopathy mouse model and induced tau aggregates in brain, while genetic ablation of APOE attenuated tau-induced neurodegeneration." (PMID 32677986, 2020). "Independently, in a mouse model of tauopathy-mediated neurodegeneration, reducing microglial activity through pharmacological methods increases soluble APOE, reduces tauopathy and rescues neurodegeneration in APOE4 mice." (PMID 32005122, 2020). "ApoE−/− mice showed typical signs of tauopathy indicated by increased numbers of AT8 positive cells (arrows) when compared to wt mice." (PMID 33029684, 2020). "Further investigations came from tau/APOE models that were generated by either crossing the tauopathy P301S mouse model with or AAV gene delivery of P301L tau into human APOE-TR models that are isoform specific." (PMID 32899606, 2020). "APOE ε4 has been shown to increase tau-mediated neurodegeneration in P301S mice, and in several human tauopathies." (PMID 31362787, 2019). "APOE4 has been also linked to other tauopathies such as corticobasal degeneration (CBD), progressive supranuclear palsy (PSP), and Pick’s disease strengthening the fact that APOE can regulate the τ in both Aβ-dependent and -independent ways." (PMID 32269835, 2019). "Sixth, astrocytes appear to influence the degree of microglial reactivity in mouse models of brain β-amyloidosis and tauopathy in an apoE isoform-dependent fashion (E4 > E3 > E2)." (PMID 29922147, 2018). "To further investigate the effects of APOE genotype on the frequency of tauopathy in humans, we studied 994 PSP patients, 134 CBD patients, and 1406 controls." (PMID 30348994, 2018). "To pursue this issue, we fed ApoE−/− mice caloric-restricted for a long-term to raise hepatic as well as neuronal Fgf21 with the aim to prevent tauopathy via the AMPK/mTOR pathway and to improve cognitive performance." (PMID 27902456, 2016). "In many tauopathies, tau is hyperphosphorylated and released from MT, ApoE, Src, and possibly other binding partners, resulting in loss of tau function." (PMID 24618580, 2014).
tauopathy (continued). "Furthermore, APOE ε4 exacerbates tau-mediated neurodegeneration in tauopathy models, whereas astrocytic APOE expression appears to play a key role in synaptic degeneration by promoting microglial phagocytosis of synaptic elements." (PMID 40993829, 2025). "Specifically, crossbreeding between humanized APOE Knock-in mice and the P301S tau mouse model of tauopathy (PS19 mouse overexpressing the P301S tau mutant) showed that only apoE4 expression exacerbated tau pathology and associated neurodegeneration when compared to the other isoforms." (PMID 40275327, 2025). "In Floxed APOE KI crossed with PS19 mice at 10-month of age, PS19-E4 mice demonstrated a higher degree of neurodegeneration compared to PS19-E3 mice, including increased hippocampal volume loss and tauopathy, myelin abnormalities and gliosis." (PMID 38462606, 2024). "The sex-dependent impact of the APOE genotype in neutrophil-induced microglial transition to MGnD now identified may also influence the disease course of tauopathies." (PMID 39313493, 2024). "We will also discuss how ApoE and tauopathy may converge on programming preE and AD-like health risks in women." (PMID 39857613, 2024). "We recently evaluated whether the gut microbiota regulates tau-mediated neurodegeneration by interacting with APOE isoforms using antibiotic-induced gut microbiota perturbation in an animal model of tauopathy." (PMID 38172602, 2024). "This raises the question of whether the relationship between ApoE and tauopathy is direct or modulated by other factors including amyloidosis." (PMID 39857613, 2024). "Using unbiased lipidomics coupled with immunostaining, a recent study demonstrated that apoE ε4 promotes cholesterol ester accumulation in the endolysosomal compartment of microglia of aged P301S tauopathy mice when compared to P301S mice expressing apoE ε3 or apoE KO animals." (PMID 39031528, 2024). "To discover whether the presence of human ApoE isoforms might affect microglial function in the setting of tauopathy, we added 4 μg/ml purified ApoE3 or ApoE4 protein to cultured BV2 cells for 6 h with 10% FBS, to ensure cholesterol loading." (PMID 39468688, 2024). "Moreover, neuronal expression of APOE4 drives a specific DAM subset with potent neurodegenerative effects in an APOE4-expressing tauopathy mouse model, an effect that can be circumvented via neuron-specific ApoE deletion." (PMID 38594240, 2024). "Though not resolved in placental tissues yet, ApoE4 or absence of ApoE can induce similar vascular dysfunction-hypoxia-mediated tauopathy associated with preE." (PMID 39857613, 2024). "In other mechanistic studies in the context of tauopathy, the ApoE-mediated neurodegeneration could be achieved by modulating microglial activation instead of tau-induced direct neurotoxicity." (PMID 39857613, 2024). "We also highlighted the novel role of the Pin1-cis P-tau-ApoE axis in the development of preE, and propagation of cis P-tau-mediated abnormal protein aggregation (tauopathy) from the placenta to cerebral tissues later in life, leading to neurodegenerative conditions." (PMID 39857613, 2024). "To further analyze the effects of HMGB1 inhibitor treatment in APOE-tauopathy mice, we performed single-nucleus RNA sequencing (snRNA-seq) on hippocampi isolated from 9.5-month-old PS19-E4 and PS19-E3 mice that underwent a 12-week treatment with the HMGB1 inhibitors or saline." (PMID 37863057, 2023). "Expression of human APOE isoforms have differential effects on cognitive function, neuroplasticity, gliosis, neurodegeneration, Aβ pathology and tauopathy in preclinical mouse models—mice expressing APOE4 are generally more vulnerable compared to APOE2 or APOE3 expressing mice." (PMID 35440098, 2022). "Given that tauopathy is broadly believed to be spread in a prionoid manner, our primary goal here was to characterize the induction and early stage progression of tau pathology in APOE mice seeded with recombinant tau prions." (PMID 35440098, 2022).
tauopathy (continued). "Furthermore, a recent study showed that glypican-4 (a binding partner of APOE-ε4) secreted by astrocytes, induced tau hyperphosphorylation in a mouse tauopathy model." (PMID 36362415, 2022). "Elevated levels of cholesterol observed in neural cells of APOE ε4 carriers, in tandem with increased tauopathy due to defects in cholesterol metabolism, suggest heightened cholesterol levels may promote tau propagation." (PMID 33815065, 2021). "This may reflect intricate interactions between age, sex, and APOE-ε4, involving pleiotropy, tauopathy, and estrogen response of APOE." (PMID 34122051, 2021). "However, another study suggested that neuronal ApoE expression is linked to MHC-I upregulation, which causes tauopathy and selective neurodegeneration." (PMID 34575087, 2021). "LRP1, as a major receptor of tau species and ApoE, may play an intermediate role between ApoE and tau species, which could point to a therapeutic potential for treating tauopathies via LRP1 interaction." (PMID 33672982, 2021). "ApoE exacerbates tau-associated neurodegeneration by driving microglial activation.However, how apoE regulates micro-glial activation and whether targeting apoE istherapeutically beneficial in tauopathy is unclear." (PMID 34612709, 2021). "Consistently, tauopathy as demonstrated in ApoE−/− mice may be contributing to alterations of [18F]FDG-PET signal in these mice although other factors such as synaptic dysfunction unrelated to tauopathy may play a role as well." (PMID 33029684, 2020). "In mouse studies, both APOE4 as well as APOE2 increased tauopathy burden in two different mouse models, raising intriguing possibilities of how APOE might interact with tau in the presence of co-morbidities (such as Aβ and α-synuclein)." (PMID 32005122, 2020). "Future studies into detailed mechanisms underlying the relationship of CLU with tau, perhaps in concert with apoE, may advance our understanding of AD and other tauopathies." (PMID 33261653, 2020). "On the other hand, there is a current lack of consensus regarding the relationship between tauopathy and APOE isoform as demonstrated by studies showing a pathogenic interaction of tau to APOE4 or APOE2." (PMID 32005122, 2020). "It remains to be elucidated whether CLU and apoE impact the tau accumulation through the same mechanism in human tauopathies." (PMID 33261653, 2020). "Our results indicate that APOE ε4 status has the most dramatic influence on tauopathy (NFT burden) and that although APOE genotype is also associated with β-amyloidosis, synucleinopathy and cognition, these relationships are largely confounded by their correlation with tangle burden." (PMID 33376986, 2020). "To investigate the behavior of microglial cells in a tauopathy disease context in vivo, we used the transgenic Tg(HuC-hTauP301L:DsRed) zebrafish model of Tau-induced neurodegeneration, combined with the transgenic Tg(ApoE-eGFP) microglia marker line." (PMID 31787873, 2019). "ApoE4 may also play an important role in tau pathogenesis, since a recent study in a murine model of tauopathy co-expressing human ApoE4 led to a significant increase in neurodegeneration compared to that seen with other ApoE isoforms." (PMID 31130847, 2019). "little information on the effects of ApoE on primary tauopathies and FTD was available." (PMID 30949567, 2019). "Since APOE is expressed in both astrocytes and microglia, cell-type specific knock-in or knockout models would contribute greatly towards determining the role of different cell types in tauopathy." (PMID 31277708, 2019). "However, our human genetic and pathological data supporting an APOE ε2 effect on tauopathy are consistent with the findings from our model studies." (PMID 30348994, 2018). "The present results suggest that neither APOE ε2 nor ε4 alleles correspond to the neurodegeneration or tauopathy observed in SNAP." (PMID 29190651, 2017).
tauopathy (continued). "In addition, the phosphorylation-dependent binding and subsequent degradation of Reelin-modified ApoE isoforms by LRP8 affects the interaction dynamic, and notably, ApoE4 competes with Reelin for this receptor, limiting Reelin signals, leading to increased tauopathy and amyloidogenesis." (PMID 40806482, 2025). "Importantly, these APOE- and IL-17-driven neutrophil-microglial interactions might extend to other neurodegenerative diseases, including tauopathies characterized by aggregation of phosphorylated TAU protein without amyloid-beta pathology." (PMID 39313493, 2024). "Thus, understanding the molecular mechanisms of apoE in the context of tauopathy might provide critical information on developing strategies for AD and other tau-related neurodegenerative diseases." (PMID 36348357, 2022). "Therefore, the relevance of ApoE isoforms in tauopathy requires further investigation." (PMID 34475505, 2021). "In our study, after excluding H1/H1 subjects, the presence of APOE ε2/ε2 genotype further increased the risk of PSP and CBD, suggesting that the association of APOE ε2/ε2 and tauopathy may be independent of MAPT H1 haplotype." (PMID 30348994, 2018). "However, in a study investigating PS19 mice with TREM2 KO, researchers found a reduction in brain atrophy in the absence of any changes in tauopathy or a reduction of MGnD-associated markers APOE and Cst7." (PMID 29311768, 2017). "To investigate the relationship between APOE4 and HMGB1 in the setting of tauopathy, we utilized a compound mouse model with humanized APOE and transgenic Tau-P301S expression." (PMID 37863057, 2023). "We analyzed how the induction of K18-seeded tauopathy influenced the proliferation of microglia and astrocytes in PS19 mice homozygous for APOE." (PMID 35440098, 2022). "APOE and its isoforms remain the most heavily explored HDL components in tauopathy in the context of AD, although both CSF APOA-I and APOJ levels have been associated with CSF tau or p-tau levels." (PMID 32899606, 2020). "demonstrates that ApoE4 modifies tauopathy independent of Aβ, raising the question whether ApoE genotype also influences risk or modifies the clinical phenotype in patients with primary tauopathies." (PMID 30949567, 2019). "The lack of a Gal3-dependent TREM2/APOE response indicates that Gal3 affects EV dynamics and tauopathy without directly intersecting with the TREM2/APOE signaling pathways." (PMID 37988169, 2024). "In line with the previous findings, in the P301S mouse model of tauopathy, together with knock-in or knockout APOE, APOE4 expressing mice showed the strongest tau-induced neurodegeneration compared to the other two isoforms, whereas APOE knockout mice were protected from this effect." (PMID 36153580, 2022). "Our analyses of neuropathology highlighted two independent pathways from APOE ε4, one where β-amyloid accumulation co-occurs with the development of tauopathy, and a second characterized by direct effects on tauopathy independent of β-amyloidosis." (PMID 33376986, 2020). "In this section, we will briefly discuss the role of APOE in amyloidogenesis and tauopathy irrespective of neuronal signaling, along with recently developed insight into the effects of APOE on autophagy and mitochondrial function." (PMID 32269835, 2019). "To determine the effects of apoE isoforms on the behavioral performance of AAV-TauP301L model, we evaluated exploration and anxiety-related behaviors, as well as learning and memory that are often abnormal in various human tauopathies." (PMID 30348994, 2018). "In late onset AD cases stratified by APOE genotype, TMCC2 immunoreactivity was associated with dense core senile plaques and adjacent neuronal dystrophies, but not with Aβ surrounding the core, diffuse Aβ plaques or tauopathy." (PMID 39084860, 2025). "Notably, this ventricular enlargement is absent in female APOE3-TREM2 R47H tauopathy mice, suggesting that APOE isoform differences influence the impact of TREM2 R47H on neurodegeneration." (PMID 40247363, 2025).